CTLA4 (cytotoxic T-lymphocyte associated protein 4)
Diseases named in the same sentence as CTLA4 in open-access papers (continued):
Sharing a sentence is not in itself a finding about the gene and the disease.
tumor (continued). "Therefore, based on the detection of the composition of infiltrated immune cells in the TME, targeting the dominant infiltrated immune cell population is a rational strategy to precisely suppress tumor growth rather than simply depending on blockade of CTLA4 or the PD1/PDL1 axis." (PMID 38016957, 2023). "Since CTLA-4 is a key mediator of Treg suppression, it is possible that inhibition of Treg function by anti-CTLA-4 antibodies might prevent expanded Treg from limiting anti-tumour immunity in these individuals, perhaps explaining why therapies targeting both PD-1 and CTLA-4 work well together." (PMID 36818683, 2023). "However, soluble cytotoxic T-lymphocyte antigen 4 (sCTLA-4), one of the isoforms of CTLA-4, plays an important role in down-regulating the negative signal of CTLA-4 in T-cell responses and studies have suggested the favourable prognostic value of serum sCTLA-4 level in tumor patients." (PMID 36879122, 2023). "In addition, since CTLA-4 is also expressed in T-reg cells, blocking this immune checkpoint could reduce the ratio of T-reg to effector T-cells in the TME leading to better control of the tumor by the immune system." (PMID 38201559, 2023). "Considering HPV-positive metastases, the density of intra-tumoral CTLA-4+ T cells and the percentage of PD-L1+ macrophages interacting with PD-1+ T lymphocytes within the tumor regions were higher in females than in males, while the percentage of HLA-I negative tumor cells was lower." (PMID 36123711, 2022). "A shift in focus to research and development of novel ICIs which target antigens that are not shared amongst both the myocardium and tumor in question, unlike the current targets PD-1, PD-L1, CTLA-4, and LAG-3 may limit inflammatory reactions against cardiomyocytes." (PMID 36185227, 2022). "Moreover, tumor cells remained suppressed after re-inoculation of mice with tumor cells, suggesting that CPI-444 induces systemic antineoplastic immune memory and that the combination of CPI-444 with CTLA-4 mAb increases the presence of CD8+T cells and IFNγ and Gzm B levels in tumors." (PMID 36159861, 2022). "In addition, increased LAG3 and CTLA4 expressions in the high-PYCARD group suggested the presence of a suppressive immune microenvironment and exhaustions of active immune cells, which may promote immune escape and tumor progression." (PMID 36291776, 2022). "Coadministration of anti-PD-1, anti-PD-L1 and anti-CTLA-4 antibodies or treatment of anti-PD-1/PD-L1/CTLA-4 trispecific antibodies may be candidate approaches to completely unleash innate and adaptive immunity to eradicate tumors, which also fits well with cancers with PD-1+ tumor or myeloid cells." (PMID 35663968, 2022). "In this study PD-1, TIM-3, LAG-3, CTLA-4 and PD-L2 were significantly upregulated on tumour-infiltrating T cells compared with peripheral circulating T cells in OAC patients, which might reflect a more exhausted T cell phenotype mediated by IC-intrinsic signalling in the tumour microenvironment." (PMID 35366537, 2022). "Furthermore, in the B16F10 melanoma tumor model, neither an anti-CTLA-4 VHH single-domain nanobody lacking the Fc-portion nor a pegylated VHH controlled tumor growth in combination with GVAX, while a VHH fusion to mIgG2a restored therapeutic efficacy with reduction of intratumoral Tregs." (PMID 35237846, 2022). "Interestingly, OVs induce a strong antiviral tumor immune response through the production of cytokines like type-1 interferon that in turn promotes PD-L1 expression on tumor cells and also cytokines, such as CCL3 and CCL4, attracting PD-1+ or CTLA-4+ immune cells within TME." (PMID 35392236, 2022). "Interestingly, the SUV intensities decreased in the rats receiving Protein vaccine-II, but not CTLA4-PD-L1-II DNA, suggesting Protein vaccine-II may serve as a tumor vaccine to prevent TAA-induced tumorigenesis of iCCA in rats." (PMID 36341387, 2022).
tumor (continued). "Interestingly, FDX1 was significantly negatively correlated with the expression of many immune checkpoint genes in ACC, especially PD-1 (PDCD1), PD-L1(CD274), CTLA4 and other important immunotherapy targets, which may also be closely related to the immune escape mechanism of ACC tumor cells." (PMID 35991547, 2022). "Thus, we demonstrate that Fc-independent functions of anti-CTLA-4 antibodies contributed to anti-tumor efficacy, which may indicate that non-Treg depleting activity of anti-CTLA-4 therapy could benefit cancer patients in the clinic." (PMID 35237846, 2022). "Indeed, the up-regulation of TIM-3 and CTLA-4 on T lymphocytes driven by HLA-G may be dampened by the inhibition of HLA-G/ILT2 interaction, thus increasing the re-activation of T cell responses against tumor cells." (PMID 35328349, 2022). "Our interesting finding of CTLA-4 overexpression (but not PD1 or PDL1) in immune cells adjacent to PDAC tumor cells, provides compelling evidence that spatial information might be used to guide immunotherapy selection, but this requires additional investigation." (PMID 35836806, 2022). "Indeed, the approval of blocking antibodies against CTLA-4, PD1 or its ligand PDL1 was a major breakthrough in immune therapy and had a strong impact on the treatment of patients suffering on metastatic melanoma, lung cancer and several other tumor entities 1-3." (PMID 35198053, 2022). "Therefore, cluster 2 of CM was considered the hot tumor to respond to immunotherapy because cluster 2 of CM displayed the characteristics of hot immune tumors, such as a high degree of CD8+ T cells, high immune score, more active immune functions, and higher expression of CTLA4, TIM3, and LAG3." (PMID 36199579, 2022). "In addition to promoting tumor growth via formation of vasculature, VEGF-A has also been shown to promote an immunosuppressive TME via upregulation of Tregs, promotion of M2 TAM, and enhancement CTLA-4 and PD-1 signaling for suppression of CD8+ T cells in murine models." (PMID 36497422, 2022). "Thus, the combinative treatment with anti-CTLA-4 plus anti-PD-1 or anti-PD-L1 should lead to the creation of an immunogenic tumor microenvironment with clinical benefits for patients regardless of their tumor original PD-L1 expression levels." (PMID 33854633, 2021). "There is evidence that T cells lose their effector function and ability to kill tumor cells when stimulated by tumor antigens, which may be due to the increasing diversity and number of inhibitory receptors, including CD274, PDCD1LG2, HAVCR2, CTLA4, LAG3, PDCD1, TIGIT." (PMID 33592580, 2021). "Biomarkers arising from the study of anti-PD-1/CTLA-4 non-responding patients or from those patients who acquire resistance might also identify suitable immunotherapy targets to re-engage anti-tumour immune activity when anti-PD-1/CTLA-4 approaches become inert." (PMID 33262520, 2021). "We observed significant anti-tumor effects of all the anti-PD-L1, anti-PD-1 and anti-CTLA-4 mAbs on tumor cells even in the absence of T-cells, thus supporting the hypothesis that ICs could play an additional role in promoting tumor cell survival and proliferation." (PMID 34201082, 2021). "Anti-tumor effects could be increased by combining the PD-1/PD-L1 blockade with other approaches (inhibitors of tyrosine kinase, PI3K/mTOR or JAK/STAT3 pathways, p300/CBP; anti-RANKL and/or anti-CTLA-4 antibodies; cytokines; nitroxoline; DNA/cell vaccines; radiotherapy/Radium-223)." (PMID 34830179, 2021). "CTLA-4 can inhibit the proliferation of T cells mainly in lymph nodes at the initial stage of the immune response, while PD-1 plays a crucial role in peripheral tissues including tumor tissue by suppressing previously activated T cells at the later stages of this response." (PMID 34899747, 2021).
tumor (continued). "The tumor-infiltrating RORC-Tregs we have shown to be linked to poor patient outcomes and associated with tumor androgenesis were selected based on elevated levels of FOXP3, CTLA4, GITR, RORC and GATA3 transcripts in the whole tumor, not from individual T-cells." (PMID 34681642, 2021). "However, pH-sensitive CTLA-4 mAbs maintain their bioavailability that is not degraded by the lysosomal, recirculate to the Treg surface, reduce adverse immune events, and exert high anti-tumor efficacy in the TME." (PMID 34806028, 2021). "Anti-tumor effects could be increased by combining PD-1/PD-L1 blockade with other approaches (inhibitors of tyrosine kinase, PI3K/mTOR or JAK/STAT3 pathways, p300/CBP; anti-RANKL and/or anti-CTLA-4 antibodies; cytokines; nitroxoline; DNA/cell vaccines; radiotherapy/Radium-223)." (PMID 34830179, 2021). "However, CTLA-4 expressed in tumor cells was not related to the prognosis of ICC." (PMID 34526987, 2021). "Interestingly, in patients with HCC, immune checkpoint-related molecules (PD-1, PD-L1, and CTLA-4) are usually overexpressed due to long-term chronic inflammation, resulting in the apoptosis of CD8+ T cells and a decreased activity of these cells against tumor." (PMID 34899747, 2021). "Similarly, expression of the granzyme B T-cell activity marker and immune checkpoint proteins programmed death (PD)-1 and cytotoxic T-lymphocyte antigen (CTLA)-4 did not significantly decrease with either treatment based on immunohistochemistry or on protein levels in tumor lysates." (PMID 33731699, 2021). "The PD-1/PD-L1 pathway regulates T cell activation during inflammatory processes, while CTLA-4 is a protein receptor on T cell surface, inhibiting T cell activity during the priming phase; miR-424 may inhibit the PD1/PD-L1 and CD80/CTLA-4 activity, inducing tumor suppression." (PMID 34830196, 2021). "Finally, therapy using anti–PD-1 and anti–CTLA-4 monoclonal antibodies, important checkpoints of the immune response, has demonstrated to play an important and valid approach to treat some types of cancer, where it is assumed primarily to enhance CD8+ T cell–mediated tumor destruction." (PMID 33013888, 2020). "Fourth, in addition to PD-L1, PD-1, and CTLA-4, TMEs of GBM may also contain other immunosuppressive factors, such as the A2aR high-affinity adenosine receptor (on lymphocytes and tumor-associated macrophages) or PD-L2 (on macrophages lacking PD-L1 expression)." (PMID 32765489, 2020). "The mode of action of CTLA-4 blockade in humans has not been elucidated completely, but it is likely to involve an expansion of the T-cell repertoire, most likely dependent on an intact process of tumor antigen cross-presentation in secondary and tertiary lymphoid structures." (PMID 33182610, 2020). "Since we found that the anti-tumor effects of 25 and 50 mg/kg OXi4503 are somewhat similar, and superior to the lower OXI4503 doses or the CA4P dose used, it might suggest that the enhancement seen in combination with anti-CTLA-4 only occurs when a specific level damage is obtained." (PMID 32640548, 2020). "Although CTLA-4 is known to regulate the primary immune response to antigen exposure, there is still no consensus on whether Ipi therapy enhances anti-tumor immunosurveillance by boosting pre-existing neoantigen-specific CD8+ T-cells or priming CD8+ T-cells against new tumor epitopes." (PMID 31568531, 2019). "Moreover, we found a significantly increased mRNA expression of the suppressive surface marker CD278 (Icos) in total lung cells derived from tumor bearing STAT1 KO mice compared to tumor bearing wild-type mice but no alteration was found on Ctla4 mRNA expression between both mice strains." (PMID 30647851, 2018). "Therefore, in this female-biased immune scenario, we may hypothesize that the lack of T cell activation rather than CTLA-4-mediated T cell inhibition is responsible for tumor escape from immune surveillance." (PMID 30545122, 2018).
tumor (continued). "One is that the AE17M tumor model did not respond to intravenous (i.v.)immunotoxins; thus, we were unable to evaluate whether i.v. immunotoxin sensitizes tumors to the therapeutic effect of anti-CTLA-4." (PMID 30441807, 2018). "We hypothesized that autocrine and paracrine TGFβ signaling in the localized microenvironment of tumor-infiltrating T cells could skew them toward Tregs and attenuate the activation of TH1 and CD8+ immune effector cells, thereby limiting the therapeutic efficacy of CTLA-4 or PD-1/PD-L1 antagonists." (PMID 29467463, 2018). "Of note, the heterogeneity of values was shown to be significantly higher for PD-1 and CTLA4 methylation possibly indicating that methylation levels do not reflect the rather homogenous tumor tissue but might be distorted by PD-1 and CTLA-4 expressing infiltrating immune cells." (PMID 29396294, 2018). "Anti-CTLA-4 antibody primarily effects CD4+ T cells at the priming phase of the immune response, while anti-PD-1/PD-L1 acts predominantly on exhausted T cells within the tumour, which might be essential for overcoming the more immunosuppressive microenvironment in late-stage solid tumours." (PMID 30410056, 2018). "In addition, CTLA-4 is expressed on both regulatory and activated T cells, and by blocking of CTLA-4 on both CD8+ T cells and Tregs, a synergistic effect can lead to maximal anti-tumor activity, through enhancement of CD8+ T cell effector function together with inhibition of Treg function." (PMID 29037250, 2017). "However, the expression of CTLA4 by tumor cells has not been sufficiently studied." (PMID 28038471, 2017). "Furthermore, combinatorial drug treatment with immune checkpoint inhibitors (anti-CTLA-4 and anti-PD-1) and epigenetic modulators (5-azacytidine and Entinostat) showed remarkable eradication of CT26 colorectal tumors and 4 T1 mammary tumors in more than 80% of the tumor-bearing mice." (PMID 28148257, 2017). "Moreover, CTLA-4 expression in cores from central tumor and invasive margin may have differing prognostic value, but consistent sampling from distinct tumor areas within the tumor epithelial compartment were not included in the TMAs in this study." (PMID 28707078, 2017). "Consequently, when CTLA-4 inhibitor was applied, CD4+T-cell proliferative capacity was enhanced, and the Treg/CD4+ T ratio was lowered although Treg numbers were not affected, which restored T-cell functional defects and produced stronger anti-tumor response in vitro." (PMID 27756892, 2017). "For mice with their primary tumours removed by surgery, the secondary tumours in both tumour model showed rather rapid growth, whose speed could only be slightly delayed if the mice were either s.c. injected with PLGA-ICG-R837, or i.v. injected with anti-CTLA4." (PMID 27767031, 2016). "Because the main problem encountered with anti-CTLA-4 treatment is the resistance of advanced tumours, due to the strong tumour-induced T cell tolerance, effectiveness of DC-based therapy could be improved by combination with immune checkpoint inhibitors that target PD-1/PDL-1 or B7/CTLA-4 pathways." (PMID 27212807, 2016). "Interestingly, the same experiments performed in the parental TRAMP model show only a modest activation of PSA-specific T cells upon anti-CD25 and anti-CTLA-4, and no survival benefit, suggesting the requirement of a tumor-specific antigen for this anti-tumor response." (PMID 26500653, 2015). "In addition, doxorubicin-based in situ vaccination strategy combined with anti-CTLA-4 and anti-OX40, an agonistic antibody against the stimulatory checkpoint molecule OX40, has been shown to improve T cell infiltration into distant tumors, leading to tumor eradication and increased survival." (PMID 26350600, 2015).
tumor (continued). "Moreover, given an adequate number of preexisting active T cells in the Group 1 tumor microenvironment, the balance between CD28/B7 positive and CTLA-4/B7 negative regulatory signals may be overthrown by CTLA-4 blockade, thus evoking excessive immune response and immunity-related toxicity." (PMID 25893809, 2015). "In addition, although further investigation is needed, 64Cu-DOTA-anti-CTLA-4 mAb could be used in the diagnosis of other types of tumor invaded by T cells, regardless of CTLA-4 expression in the tumor cells." (PMID 25365349, 2014). "Moreover, CTLA-4 has been described to play a negative role in tumor progression or persistence." (PMID 25090912, 2014). "Antibodies targeting PD-1 and/or CTLA-4 (blocking the negative costimulatory molecules and then boosting the T-cell function) could improve the adoptive transfer efficiency and lead to a clinical benefit in patients with high tumor burden." (PMID 24741578, 2014). "In addition to CTLA-4, tumor infiltrating lymphocytes may express the negative regulatory receptors PD-1, LAG-3, TIM-3 and others." (PMID 24829749, 2013). "Several studies have focused on tumour-localized rather than systemic administration of anti-CTLA-4 to specifically expand lymphocytes at the tumour site, with some success and this strategy could be applied to the vaccine regimen reported here to further enhance efficacy." (PMID 23799135, 2013). "This is supported by several pre-clinical tumor models, showing that CTLA-4 blockade on its own is not very potent in triggering a specific anti-tumor response, but when combined with agents that prime immune responses, such as DC vaccination, it might become very effective." (PMID 24348481, 2013). "The main problems encountered with anti-CTLA-4 treatment are the resistance of advanced tumors, due to a strong tumor-induced T cell tolerance, which may be partially PD-1 pathway mediated, and a lack of tumor specificity." (PMID 24348481, 2013). "Since anti-CTLA-4 antibody is known to be ineffective against poorly immunogenic tumors but to synergize with vaccination in inducing anti-tumor immunity, these data imply that radiation used as single dose of 20 Gy failed to convert the tumor into an in situ vaccine." (PMID 23112958, 2012). "The presence of CTLA4 may explain the lack of tumor reduction despite infiltrating immune cells." (PMID 22013484, 2011). "Similarly, targeting molecules on tumor-specific T cells that are involved in the regulation of T cell survival and effector functions (e.g., IL-7, IL-15, activating antibodies to CD137, blocking CTLA-4) might translate into improved clinical outcomes." (PMID 24212804, 2011). "IPI-549 or PD-L1 single or dual treatments did not affect PD-1, CTLA-4, TIGIT, LAG-3, or TIM-3 expression in tumor-infiltrating CD4+ T-cells in HNSCC tumor-bearing mice." (PMID 41431358, 2026). "While the marker of proliferation, MKI67, was increased in tumor samples, DIPG tumor samples showed no significant upregulation of immune checkpoint markers PD-L1 (CD274) and CTLA-4 compared to matched normal tissue." (PMID 41541220, 2026). "By contrast, PD‐1/CTLA‐4 dual blockade neither restored CD4+ T cell infiltration nor enhanced IFN‐γ and Granzyme B production, consistent with its limited anti‐tumour activity." (PMID 41492119, 2026). "The expression of TIM-3, as well as PD-1, LAG3, and CTLA-4, are higher on T cells in HCC tumor tissue compared with normal liver tissue." (PMID 40076561, 2025). "Thus, to overcome tumor resistance, various studies have evaluated new potential markers that converge to discriminate between responders and non-responders to anti-PD-1/anti-CTLA-4 therapy, helping to stratify patients suitable for the most effective immunotherapy." (PMID 40564098, 2025). "By generating a fresh wave of tumor-specific T cells, ICD can sensitize “cold” tumors (lacking immune infiltrate) to ICIs like anti-PD-1 and anti-CTLA-4 antibodies, which work by “releasing the brakes” on already-present T cells." (PMID 41235238, 2025).